CCDC80 (coiled-coil domain containing 80)
Description:
Promotes cell adhesion and matrix assembly.
Synonyms: DRO1; URB; SSG1; CL2; TCONS_00006930; LINC01279; okuribin
Tractability: Antibody: UniProt places it where antibodies can reach, with medium confidence; UniProt predicts a signal peptide or a membrane-spanning region; its Gene Ontology location is reachable by antibodies, with medium confidence. PROTAC: UniProt records ubiquitination sites on it; ubiquitination databases record sites on it.
Gene: Protein-coding gene on chromosome 3 (112,596,797 to 112,649,530, reverse strand). Ensembl gene ENSG00000091986.
Subcellular location: Secreted, extracellular space, extracellular matrix
Gene Ontology:
Molecular function: fibronectin binding; glycosaminoglycan binding; heparin binding
Biological process: extracellular matrix organization; positive regulation of cell-substrate adhesion
Cellular component: basement membrane; extracellular matrix; interstitial matrix
Genetic constraint (gnomAD): Loss-of-function variants: 46 observed, 78.57 expected, observed/expected ratio (o/e) 0.59, 90% interval 0.46 to 0.75. The upper end of that interval is the gene's LOEUF score, 0.75, which puts it in group 3 of 6, group 1 being the genes least tolerant of losing a copy. Missense variants: 1,182 observed, 1,242.1 expected, observed/expected ratio (o/e) 0.95, 90% interval 0.91 to 1. Synonymous variants: 484 observed, 464.85 expected, observed/expected ratio (o/e) 1.04, 90% interval 0.97 to 1.12.
Homologues: Orthologues: chimpanzee CCDC80 (99% identical), macaque CCDC80 (98% identical), pig CCDC80 (88% identical), guinea pig CCDC80 (86% identical), rabbit CCDC80 (85% identical), rat Ccdc80 (84% identical), mouse Ccdc80 (84% identical), dog CCDC80 (74% identical).
Diseases named in the same sentence as CCDC80 in open-access papers:
CCDC80 is named in the same sentence as 56 diseases in open-access papers, as found by Europe PMC text mining. Sharing a sentence is not in itself a finding about the gene and the disease. The quoted sentences say what the papers report.
colorectal cancer (10 papers, 2018 to 2025). A primary or metastatic malignant neoplasm that affects the colon or rectum. "Similarly, CCDC80 has been associated with acquired drug resistance and immune infiltration in colorectal cancer." (PMID 36556227, 2022). "In ApcMin/+ mice and chemically-induced colorectal cancer models, Dro1/Ccdc80 has been proven to be an effective suppressor of colorectal cancer." (PMID 38872096, 2024). "Currently, DRO1/CCDC80 has been identified as a tumor suppressor in the tumor microenvironment, and DRO1/CCDC80 activation in the stroma inhibits colorectal cancer growth and promotes the apoptosis of cancer cells." (PMID 36387195, 2022). "Dro1/Ccdc80 has been shown to be a potent suppressor of colorectal cancer and ubiquitous inactivation of Dro1/Ccdc80 strongly promoted colorectal carcinogenesis in ApcMin/+ mice and in a chemically-induced colorectal cancer model." (PMID 35422964, 2022). "To study the effect of microenvironmental Dro1/Ccdc80 on colon tumorigenesis, we injected parental MC38 colorectal cancer cells subcutaneously into Dro1−/− and Dro1+/+ control mice." (PMID 35422964, 2022). "Related studies have shown that CCDC80 can be used as a prognostic stem biomarker to regulate the acquired drug resistance and immune infiltration in colorectal cancer." (PMID 36387195, 2022). "Microenvironmental down-regulation of DRO1/CCDC80 was found in 80% of human colorectal cancer specimens." (PMID 35422964, 2022). "Previously, we have demonstrated DRO1/CCDC80 to be down-regulated in the majority of primary human colorectal carcinoma specimens." (PMID 35422964, 2022). "In previous studies, CCDC80 was reported as a prognostic signature in serous ovarian carcinoma, colorectal cancer, and muscle-invasive bladder cancer." (PMID 34820451, 2021). "Additionally, in colorectal cancer, CCDC80 acted as a suppressor of tumor growth, with research indicating that it involved the phosphorylation of ERK14." (PMID 39308689, 2024). "Since Dro1/Ccdc80 mRNA level was found to be reduced in murine cancer associated fibroblasts, we investigated expression of DRO1/CCDC80 in micro-dissected stroma from human primary colorectal cancer compared to expression in adjacent normal intestinal stroma." (PMID 35422964, 2022). "Consistently, loss of DRO1/CCDC80 in PSC did not affect the growth of three-dimensional tumor spheroids generated by aggregation of MC38 colorectal cancer cells and PSC." (PMID 35422964, 2022). "Using transcriptional profiling, previous publications have identified that CCDC80 may play a role in tumor inhibition, such as ovarian cancer, malignant melanoma, thyroid and colorectal carcinoma." (PMID 31992220, 2020). "Since loss of stromal DRO1/CCDC80 facilitates migration of intestinal epithelial cells, stromal DRO1/CCDC80 might probably regulate transition from a stationary cancer stem cell into a migrating cancer stem cell during the multistep progression of colorectal cancer." (PMID 35422964, 2022). "Expression analyses showed Dro1/Ccdc80 to be significantly down-regulated in murine gastric cancer associated fibroblasts, in ApcMin/+ colon tumor primary stromal cells and in microdissected stroma from human colorectal cancer compared to normal, non-tumor stroma." (PMID 35422964, 2022). "We found Dro1/Ccdc80 to be significantly down-regulated in ApcMin/+ colon tumor primary stromal cells and in microdissected stroma from human colorectal cancer compared to normal, non-tumor stroma." (PMID 35422964, 2022).
Obesity (10 papers, 2009 to 2024). Accumulation of substantial excess body fat. "In a human study, CCDC80 was quantified in serum, and serum CCDC80 levels correlated positively with obesity risk, inflammation markers, and liver steatosis." (PMID 37224770, 2023). "CCDC80 seems to be linked to obesity-altered secretome in visceral adipose tissue, glucose tolerance imbalances, and associated with chronic inflammation complications." (PMID 33101375, 2020). "CCDC80 plays a key regulatory role in major physiological processes, such as weight control, energy metabolism, and apoptosis, and is closely linked to related diseases, such as obesity and insulin resistance." (PMID 37391702, 2023). "Meanwhile, a small population-based epidemiological survey has demonstrated that CCDC80 may be a component of the obesity-linked secretome in visceral adipose tissue and whose blood levels are connected to glucose intolerance and low-grade inflammation related chronic complications." (PMID 31992220, 2020). "Contrastingly, CCDC80 down-regulation was discovered in white adipose tissue in ob/ob, KKAy and diet-induced obesity mouse models." (PMID 31992220, 2020). "NOX4, CCDC80, COL1A2, HTRA1, and KLHL29 were identified as key genes by LASSO regression analysis, among which HTRA1 and KLHL29 showed a close association with immune system infiltration in DCM and obesity." (PMID 36547458, 2022). "CCDC80, an adipocyte-secreted protein, regulates glucose homeostasis in diet-induced obesity mice." (PMID 33101375, 2020). "One is the gene encoding CCDC80/URB/SSG1/DRO1, which was identified as an upregulated transcript in the adipose tissue of bombesin receptor subtype-3 (BRS-3)-deficient mice displaying mild late-onset obesity and sensitizes cells to anoikis and apoptosis." (PMID 20175888, 2010). "Given that COL1A2, closely related to CCDC80, mediates the production of fibrillar collagen, we may assume that the combined action of CCDC80 and COL1A2 promotes myocardial fibrosis and accelerates the development of cardiomyopathy in the presence of obesity risk factors." (PMID 36547458, 2022). "We speculated that circulating CCDC80 might be involved with obesity-related processes." (PMID 31992220, 2020). "CCDC80 (Coiled-Coil Domain Containing 80, also called DRO1, URB, CL2) is an extracellular matrix protein and was first found to be upregulated in the brown adipose tissue of mice with mild obesity." (PMID 39308689, 2024). "CCDC80, a protein secreted by adipocytes that regulates lipogenesis, is significantly elevated in visceral adipose tissue (VAT) in obesity." (PMID 36547458, 2022). "The key genes, NOX4, CCDC80, COL1A2, HTRA1, and KLHL29 were significantly expressed in DCM, with KLHL29 and HTRA1 especially closely associated with the immune response, which might be markers for obesity-induced DCM and be potential avenues for exploration in immunotherapy." (PMID 36547458, 2022). "CCDC80 is a secreted protein that regulates adipocyte differentiation, whereas DGAT2 is an enzyme that catalyzes the final step of mammalian triglyceride synthesis and may be involved in the mechanisms of obesity, insulin resistance, and leptin resistance." (PMID 23741331, 2013).
ovarian carcinoma (10 papers, 2020 to 2025). A malignant neoplasm originating from the surface ovarian epithelium. "Through integrated machine learning and single-cell analysis, we identified five prognostic-associated SRGs (PI3, AUP1, CD200, GNAS and CCDC80) regulated by global SUMOylation levels in ovarian cancer." (PMID 40534859, 2025). "Downregulation or loss of CCDC80 expression has been associated with multiple cancer types, including ovarian cancer, and it has been linked to poorer outcomes." (PMID 37958970, 2023). "We aimed to explore the downregulation of the coiled-coil domain containing 80 (CCDC80) and its underlying molecular mechanisms in ovarian carcinoma (OVCA)." (PMID 34820451, 2021). "On the whole, our study identified five key SRGs, including the risk genes AUP1, PI3 and CCDC80, as well as the protective genes CD200 and GNAS and elucidated their prognostic potential in ovarian cancer." (PMID 40534859, 2025). "Through single-cell analysis, we further identified five potential prognostic biomarkers associated with the ovarian cancer cell functional pathway and TIME: three risk genes PI3, AUP1 and CCDC80 and two protective genes CD200 and GNAS." (PMID 40534859, 2025). "Studies exploring the clinical relevance of CCDC80 in ovarian cancer patients are underway; they aim to elucidate its impact on disease progression and patient survival." (PMID 37958970, 2023). "In the context of ovarian cancer, CCDC80’s role in mediating cell adhesion and migration is of particular interest." (PMID 37958970, 2023). "We found that the expression intensity and quantity of PI3, RGS1, PTGER3 and CCDC80 in ovarian cancer tissue was higher than that in normal ovarian tissue." (PMID 33271935, 2020). "Studies have shown that CCDC80 expression is downregulated in ovarian cancer and may function as a tumor suppressor." (PMID 40937329, 2025). "Patients with CCDC80-positive ovarian cancer have higher CD4 + memory-resting cells infiltration." (PMID 38872096, 2024). "Targeted inhibition (such as gene therapy) to specifically reduce CCDC80 expression in CD8+ cytotoxic T cells, thereby reactivating their antitumor immune activity, has the potential to enhance the response of ovarian cancer patients to ICI treatment." (PMID 40534859, 2025). "CCDC80, also known as LRP1B (Low-Density Lipoprotein Receptor-Related Protein 1B), is gaining recognition as a candidate gene in ovarian cancer prognosis." (PMID 37958970, 2023).
gastric cancer (8 papers, 2021 to 2025). A primary or metastatic malignant neoplasm involving the stomach. "Subsequently, we further analyzed the relationship between CCDC80 and somatic gene mutations in gastric cancer patients." (PMID 38872096, 2024). "For example, deletion of CCDC80 impairs the growth-inhibitory effect mediated by LATS1/2 (Hippo pathway kinases) deficiency in MC38 cells, and silencing the immune-infiltration-associated gene CCDC80 suppresses malignant progression and tumorigenicity in gastric cancer." (PMID 40534859, 2025). "CCDC80 is associated with immune cell infiltration in highly expressed gastric cancer subtypes." (PMID 40937329, 2025). "Moreover, Dro1/Ccdc80 expression was reduced in gastric cancer associated fibroblasts with respect to normal intestinal stromal cells." (PMID 35422964, 2022). "It is recommended to further increase the number of animals or perform the knockout mouse model to explore the role of CCDC80 in gastric cancer in depth." (PMID 38872096, 2024). "Subsequently, we transfected HGC-27 and MKN-74 cells with si-CCDC80 to investigate its role in the characterization of gastric cancer." (PMID 38872096, 2024). "Silencing CCDC80 inhibited malignant characterization and subcutaneous tumor formation of gastric cancer cells." (PMID 38872096, 2024). "Next, we further investigated the role of CCDC80 silence in the development of gastric cancer cells in nude mice." (PMID 38872096, 2024). "Our research is based on the bioinformatics analysis of the TCGA dataset, which shows that CCDC80 was significantly overexpressed in the group of gastric cancer and was related to tumor immune infiltration level." (PMID 38872096, 2024). "The role of marker CCDC80 was investigated by cell and tumorigenic experiments, which provided reference for the treatment of immunoinfiltration subtypes in gastric cancer patients." (PMID 38872096, 2024). "Bioinformatics analysis showed that CCDC80, as a stemness marker, was significantly overexpressed in gastric cancer." (PMID 38872096, 2024). "By contrast, CCDC80 was downregulated in murine gastric cancer fibroblasts and seems to have tumor suppressive functions." (PMID 39695086, 2024). "On the contrary, when the stromal compartment was studied, Dro1/Ccdc80 mRNA level was abundant in C57BL/6 small intestinal stromal cells, mouse embryonic fibroblasts, and murine gastric cancer associated fibroblasts." (PMID 35422964, 2022). "CCDC80 was also related to the degree of gastric cancer immune invasion." (PMID 38872096, 2024). "Compared with Normal group, CCDC80 was significantly overexpressed in patients with gastric cancer." (PMID 38872096, 2024). "Silencing CCDC80, a prognostic biomarker in patients with immune invasion of gastric cancer, could effectively inhibit the malignant characterization, M2 polarization, and tumor formation of gastric cancer." (PMID 38872096, 2024). "Finally, the lack of extensive clinical validation and functional assays means that the clinical applicability of CCDC80 as a prognostic marker or therapeutic target in gastric cancer remains to be fully established." (PMID 39308689, 2024). "Therefore, CCDC80 is highly expressed as the oncogene in highly immunoinvasive gastric cancer subtypes." (PMID 38872096, 2024). "Cell experiments with gastric cancer cells confirmed high expression of CCDC80 in gastric cancer, proving it might serve as a biomarker for gastric cancer patients." (PMID 38872096, 2024). "Relationship between CCDC80 expression and immune infiltration was explored in gastric cancer." (PMID 38872096, 2024). "CCDC80 may be a potential target to promote chemotherapy sensitivity in gastric cancer patients with tumor microenvironment immune restriction." (PMID 38872096, 2024). "This phenomenon suggests that CCDC80 may play a complex role in T cell immunity in gastric cancer, but the specific mechanisms of action still need further exploration." (PMID 38872096, 2024).
gastric cancer (continued). "Silencing CCDC80 inhibited the development and proliferation of subcutaneous gastric cancer tumors." (PMID 38872096, 2024). "Therefore, CCDC80 was the potential biomarker for poor prognosis in gastric cancer." (PMID 38872096, 2024). "Therefore, CCDC80, as an oncogene, played a role in gastric cancer cells and might be a potential cure target." (PMID 38872096, 2024). "CCDC80 silencing can inhibit M2 polarization and the JAK-STAT pathway in gastric cancer cells and tumor tissues." (PMID 40937329, 2025). "Silencing CCDC80 also inhibited the M2 polarization and JAK-STAT pathway in cells and tumor tissue of gastric cancer." (PMID 38872096, 2024). "Finally, gastric cancer cells (HGC-27 and MKN-45) were selected to evaluate the action of silencing CCDC80 on malignant characterization, macrophage polarization, and tumor formation." (PMID 38872096, 2024).
atherosclerosis (5 papers, 2020 to 2025). A disease characterized by the build-up of fatty material and calcium deposition in the arterial wall resulting in partial or complete occlusion of the arterial lumen. "Finally, we detected that plasma CCDC80 level was positively associated with the dyslipidemia and atherosclerosis marker LDL-C, apoA1 and apoB." (PMID 31992220, 2020).
pancreatic cancer (5 papers, 2012 to 2024). "Our review of recent pancreatic cancer studies has revealed a focus on CDH1 and CCDC80 as genes that suppress EMT markers or impact EMT processes in pancreatic cancer progression." (PMID 33928036, 2021). "Collectively, these results indicate that combination treatment of vactosertib with nal-IRI/5-FU/LV improves overall survival rates in a mouse model of pancreatic cancer by suppressing invasion through CCDC80." (PMID 32076068, 2020). "Consistent with down-regulation of Ccdc80 in the pancreatic tumour tissues, mRNA expression of CCDC80 was significantly decreased in most of the pancreatic cancer cell lines compared to HPDE normal pancreatic cell line." (PMID 32076068, 2020). "In addition, vactosertib combined with nal-IRI/5-FU/LV improved survival by inhibiting CCDC80 invasion in pancreatic cancer." (PMID 38872096, 2024). "CCDC80 (downregulated by oncogenes protein 1) is a secreted tumor suppressor protein that facilitates the apoptotic cascade and mediates growth inhibition in colon and pancreatic cancer." (PMID 23213280, 2012). "We further investigated whether CCDC80 plays a role in EMT of pancreatic cancer cells." (PMID 32076068, 2020). "Collectively, these findings suggest that CCDC80 might participate in the underlying mechanism of combination treatment of vactosertib with nal-IRI/5-FU/LV in suppressing invasiveness and subsequent pancreatic cancer progression." (PMID 32076068, 2020). "CCDC80, also known as downregulated by oncogenes 1 (DRO1), is shown to be downregulated in many types of cancers, including CRC, pancreatic cancer, and thyroid cancer." (PMID 34746152, 2021). "To investigate the role of CCDC80 in pancreatic cancer progression, we generated PANC-1 and Panc02 cells stably expressing 3Flag-CCDC80." (PMID 32076068, 2020). "Overexpression of CCDC80 decreases clonogenic capacities of cancer cells, including PANC-1 and BxPC-3 pancreatic cancer cells, and increases CD95-induced apoptosis." (PMID 32076068, 2020). "Ectopic expression of CCDC80 suppressed migration and colony formation concomitant with decreased expression of epithelial-to-mesenchymal transition (EMT) markers in pancreatic cancer cells." (PMID 32076068, 2020). "In addition to these roles of CCDC80, we revealed that the ectopic expression of CCDC80 could also suppress cell migration, colony formation, and EMT in PANC-1, Panc02, and SNU2491 pancreatic cancer cells." (PMID 32076068, 2020).
melanoma (4 papers, 2020 to 2024). A malignant, usually aggressive tumor composed of atypical, neoplastic melanocytes. "CCDC80 can mediate the regulation by focal adhesion kinase (FAK) of the migration of melanoma cells and can also exert a tumor suppressor effect in thyroid cancer." (PMID 34195091, 2021). "CCDC80 mediates focal adhesion kinase (FAK) regulation of B16F10 melanoma cell migration." (PMID 38872096, 2024). "In contrast to our findings in B16 melanoma cells, CM from ApcMin/+Dro1/Ccdc80knockout PSC did not affect activity of caspase-3/7 in apoptosis induced intestinal epithelial cells, suggesting no modulatory role for DRO1/CCDC80 in apoptosis in the intestinal epithelium." (PMID 35422964, 2022).
thyroid cancer (4 papers, 2021 to 2025). "It has been reported that in human thyroid carcinoma, CCDC80 played the role as a putative tumor suppressor gene." (PMID 34805166, 2021).